LRRC10 (leucine rich repeat containing 10)
Description:
May play important roles in cardiac development and/or cardiac function.
Synonyms: HRLRRP; LRRC10A
Tractability: No criterion of Open Targets' tractability assessment is met for any kind of drug.
Gene: Protein-coding gene on chromosome 12 (69,608,564 to 69,610,907, reverse strand). Ensembl gene ENSG00000198812.
Subcellular location: Nucleus
Gene Ontology:
Molecular function: actin binding; alpha-actinin binding
Biological process: cardiac muscle cell development
Cellular component: cytoskeleton; sarcomere; mitochondrion; myofibril; nucleus
Genetic constraint (gnomAD): Loss-of-function variants: 6 observed, 12.66 expected, observed/expected ratio (o/e) 0.47, 90% interval 0.26 to 0.94. The upper end of that interval is the gene's LOEUF score, 0.94, which puts it in group 3 of 6, group 1 being the genes least tolerant of losing a copy. Missense variants: 320 observed, 373.58 expected, observed/expected ratio (o/e) 0.86, 90% interval 0.78 to 0.94. Synonymous variants: 145 observed, 161.94 expected, observed/expected ratio (o/e) 0.9, 90% interval 0.78 to 1.03.
Gene-disease validity (ClinGen):
ClinGen rates the evidence that LRRC10 causes each of these diseases.
dilated cardiomyopathy (autosomal recessive): No Known Disease Relationship. Cardiomyopathy which is characterized by dilation and contractile dysfunction of the left and right ventricles.
Homologues: Orthologues: chimpanzee LRRC10 (99% identical), macaque LRRC10 (97% identical), pig LRRC10 (94% identical), mouse Lrrc10 (88% identical), tropical clawed frog lrrc10 (68% identical), zebrafish lrrc10 (57% identical). Paralogues in human: LRRC10B (38% identical), SCRIB (31% identical), LRRC1 (29% identical), PHLPP2 (28% identical), LRRC7 (28% identical), PHLPP1 (27% identical), ERBIN (26% identical), LRRC8B (26% identical), LRRC8A (25% identical), MFHAS1 (25% identical), PIDD1 (25% identical), LRRIQ4 (24% identical), and 19 more.
Diseases named in the same sentence as LRRC10 in open-access papers:
LRRC10 is named in the same sentence as 7 diseases in open-access papers, as found by Europe PMC text mining. Sharing a sentence is not in itself a finding about the gene and the disease. The quoted sentences say what the papers report.
dilated cardiomyopathy (6 papers, 2012 to 2023). "LRRC10 is a component of a cardiac voltage-gated L-type Ca2+ channel whose mutation can cause dilated cardiomyopathy." (PMID 34968235, 2020). "In contrast, microarray analyses of adult Lrrc10−/− hearts identified upregulation of oxidative phosphorylation and cardiac muscle contraction pathways during the progression of dilated cardiomyopathy." (PMID 23236519, 2012). "We identify Lrrc10 as a novel dilated cardiomyopathy candidate gene and the Lrrc10−/− mouse model as a unique system to investigate pediatric cardiomyopathy." (PMID 23236519, 2012). "Deletion of Lrrc10 in mice results in dilated cardiomyopathy." (PMID 24278182, 2013). "Adult Lrrc10−/− hearts exhibited enrichment of upregulated transcripts from the dilated cardiomyopathy KEGG pathway (data not shown)." (PMID 23236519, 2012).
cardiomyopathy (2 papers, 2012 to 2016). A disease of the heart muscle or myocardium proper. "Moreover, generation of cardiomyocytes from patient-derived induced pluripotent stem cells (iPSCs) or human pluripotent stem cells containing DCM-linked LRRC10 mutations will serve as powerful tools to investigate human cardiomyopathy." (PMID 27536250, 2016). "In summary, Lrrc10−/− mice exhibit early-onset cardiomyopathy that develops into DCM by one month of age, with a progressive decline in cardiac function." (PMID 23236519, 2012).
cardiac hypertrophy (1 paper, 2012). "In an effort to determine molecular defects in Lrrc10−/− hearts, various signaling pathways known to mediate cardiac hypertrophy were investigated using WT and Lrrc10−/− heart extracts at 2–3 months of age." (PMID 23236519, 2012). "Lrrc10−/− hearts exhibit significant induction of the fetal genes ANF (atrial natriuretic factor, Nppa), β-MHC (β-myosin heavy chain, Myh7), and BNP (brain natriuretic peptide, Nppb), indicating pathological cardiac hypertrophy." (PMID 23236519, 2012).
idiopathic dilated cardiomyopathy (1 paper, 2016). Decreased function of the heart associated with cardiac enlargement and congestive heart failure, of unknown cause. "Recent studies have identified LRRC10 mutations in human idiopathic dilated cardiomyopathy (DCM) and Lrrc10 homozygous knockout mice develop DCM, strongly linking LRRC10 to the molecular etiology of DCM." (PMID 27536250, 2016).
cardiac disease (1 paper, 2016). "The identification of two novel mutations in LRRC10 that are associated with human idiopathic DCM has opened the door for investigation into the roles of LRRC10 in human cardiac disease and the underlying molecular mechanisms that cause DCM in response to mutation or genetic ablation of LRRC10." (PMID 27536250, 2016). "Future sequencing for LRRC10 in human idiopathic DCM will be very informative on the prevalence of LRRC10 mutations in DCM and the potential for additional mutations to contribute to human cardiac disease." (PMID 27536250, 2016). "Further sequencing of LRRC10 in human idiopathic DCM will reveal the prevalence of LRRC10 mutations in DCM and potentially identify novel mutations associated with cardiac disease in humans." (PMID 27536250, 2016). "Here, we review what is known about the cardiomyocyte functions of LRRC10, lessons learned about LRRC10 and DCM from the Lrrc10 knockout mouse model, and discuss ongoing efforts to elucidate molecular mechanisms whereby mutation or absence of LRRC10 mediates cardiac disease." (PMID 27536250, 2016). "Recently, studies in Lrrc10 knockout mice and the identification of LRRC10 mutations in human DCM have sparked interest in the underlying molecular mechanisms that mediate cardiac disease when LRRC10 is absent or mutated." (PMID 27536250, 2016).
LRRC10 also shares sentences with these, for which no sentence is quoted: aortic stenosis (1 paper); myocardial infarction (1).